RN7SL798P (RNA, 7SL, cytoplasmic 798, pseudogene)
Gene: Miscellaneous RNA gene on chromosome 8 (55,980,240 to 55,980,540, reverse strand). Ensembl gene ENSG00000240905.
Homologues: Orthologues: chimpanzee Metazoa_SRP (99% identical), macaque Metazoa_SRP (91% identical), rabbit Metazoa_SRP (72% identical). Paralogues in human: RN7SL2 (83% identical), RN7SL1 (83% identical), RN7SL3 (81% identical), RN7SL769P (80% identical), RN7SL743P (80% identical), RN7SL220P (80% identical), RN7SL625P (79% identical), RN7SL478P (79% identical), RN7SL712P (79% identical), RN7SL43P (79% identical), RN7SL709P (79% identical), RN7SL7P (79% identical), and 703 more.